INS (insulin)
Diseases named in the same sentence as INS in open-access papers (continued):
Sharing a sentence is not in itself a finding about the gene and the disease.
Hypoglycemia (continued). "The diagnosis of insulinoma is anchored in demonstrating hyperinsulinemic hypoglycemia during a supervised fasting test, where prolonged fasting triggers hypoglycemia, allowing measurement of plasma insulin, C‐peptide, and proinsulin levels." (PMID 40124204, 2025). "Our 53-year-old Caucasian female experienced both postprandial and fasting hypoglycemia, accompanied by elevated insulin levels and the presence of insulin autoantibodies." (PMID 39968421, 2025). "The comparable rates of severe hypoglycemia and glycemic control in our cohort suggest that, once insulin therapy is initiated, metabolic outcomes are more strongly influenced by behavioral, educational, and technological factors than by family history itself." (PMID 41303901, 2025). "Although dextrose is given to treat hypoglycemia, it also triggers beta cells to release insulin, which can complicate hypoglycemic episodes, making recovery challenging." (PMID 41368518, 2025). "When hypoglycemia is insulin mediated due to an insulinoma, then glucose levels are expected to rise greater than 25 mg/dL (1.39 mmol/L) within 15 minutes following the glucagon challenge." (PMID 40083398, 2025). "For localized disease, surgical resection with curative intent is the first-line approach and often leads to long-term remission, as removing the insulin-secreting tumor eliminates hyperinsulinemia and promptly corrects recurrent hypoglycemia." (PMID 40647278, 2025). "When comparing the indicators of insulin and glycemia, the frequency of hypoinsulinemic hypoglycemia was observed almost two times more often in the NC group." (PMID 40370701, 2025). "VMH activation of both AMPK and nNOS are required to restore euglycemia following insulin-induced hypoglycemia." (PMID 40181907, 2025). "Knowledge of insulin self-administration, specifically a low level of knowledge (AOR=4.87; 95% CI: 1.55-15.26), was significantly associated with self-reported hypoglycemia." (PMID 40110390, 2025). "In contrast, in HCN, despite a slowdown in the decrease in the proportion of prescriptions for SUs and insulin, the rate of decrease in the incidence of hypoglycemia was higher after 2017 than before 2017." (PMID 40777704, 2025). "Results also show that VMN Ghrh gene silencing increased proportional CYP19A1 gene transcription V- or INS-injected old and young female rats, and that in contrast to old male rats, hypoglycemia up-regulated this relative expression ratio in old females." (PMID 40613376, 2025). "Critical samples during hypoglycemia (blood sugar nadir 26 mg/dL) showed inappropriately elevated insulin and C-peptide with suppressed ketones and appropriate cortisol and growth hormone (GH) responses, while metabolic work-up was otherwise unremarkable." (PMID 41531556, 2025). "Hypoglycemia was reported in 24% of patients during the treatment period, likely due to the concurrent use of insulin or sulfonylureas with dulaglutide." (PMID 40842739, 2025). "Glucose or dextrose was added to IV fluids when blood glucose fell below 250 mg/dL, with higher concentrations (10–12.5%) used to prevent hypoglycemia during insulin therapy, adjusting based on blood glucose levels or rate of decline." (PMID 41227190, 2025). "Once partial remission ends, the reliance on exogenous insulin gradually increases, resulting in greater fluctuations in blood glucose levels and heightened challenges in preventing hypoglycemia." (PMID 40871638, 2025). "While ALA has potential therapeutic benefits for improving insulin sensitivity and mitochondrial function, its ability to induce hypoglycemia poses risks to the nervous system, especially under fasting conditions." (PMID 40699801, 2025). "Non-selective beta-blockers further complicate remission strategies by inhibiting insulin secretion through β2-receptor blockade, increasing triglyceride levels, promoting weight gain, and masking the adrenergic warning symptoms of hypoglycemia." (PMID 41427055, 2025).
Hypoglycemia (continued). "Incorrect use - If a patient forgets and applies 2x icodec, will the patient experience more hypoglycemia comparedcompared to daily insulin?" (PMID 39810242, 2025). "Hirata syndrome is the most likely diagnosis for hypoglycemia with very high levels of insulin and elevated titers of insulin autoantibodies." (PMID 40584814, 2025). "Achieving optimal glycemic control with minimal glucose variability and hypoglycemia, especially nocturnal hypoglycemia, remains a key objective in insulin therapy, particularly for patients with T1DM." (PMID 40186384, 2025). "Mechanistically, hEDS coexists with dysautonomia and rapid GI emptying, accelerating carbohydrate delivery and exaggerating secreted insulin excursions modulating reactive or postprandial hypoglycemia." (PMID 41281935, 2025). "Severe hypoglycemia is more commonly seen in patients treated with bolus insulin alone than in those treated with basal insulin alone." (PMID 40726866, 2025). "Consistent with previous research found that 100% of hospitalized type 1 diabetic patients using insulin experienced hypoglycemic episodes, and 99.4% of type 2 diabetic patients using insulin had at least one episode of hypoglycemia." (PMID 40901501, 2025). "Insulin-mediated hypoglycemia is defined based on glycemia ≤ 55 mg/dL, insulinemia ≥ 3 μU/mL, C-peptide levels ≥ 0.6 ng/mL, proinsulinemia ≥ 5 pmol/L and β-hydroxybutyrate levels ≤ 2.7 mmol/l." (PMID 39941267, 2025). "Specifically for individuals on ultra-long-acting insulin pre-exercise fructose intake can effectively prevent training-induced hypoglycemia." (PMID 39998445, 2025). "At that point, insulin had been progressively tapered and eventually discontinued due to recurrent episodes of symptomatic hypoglycemia, which persisted despite complete insulin therapy withdrawal." (PMID 41561059, 2025). "If CHO are given during PA to treat pending or actual hypoglycaemia, the rise in glucose from treatment can trigger insulin delivery even during Exercise mode." (PMID 39653802, 2025). "The resulting glycemic variability often precipitates both chronic hyperglycemic complications and, most acutely, severe hypoglycemia—a life-threatening condition that remains the primary barrier to safe and effective insulin intensification." (PMID 41471093, 2025). "Standard therapies for potassium shifting include insulin, which has been shown to induce hypoglycemia in up to 75% of patients and albuterol which commonly induces tachycardia." (PMID 41178555, 2025). "Biochemical evidence of endogenous insulin-mediated hypoglycemia is crucial, and a supervised 72 h fast is usually recommended as a standard diagnostic step." (PMID 40648766, 2025). "Serious adverse events and severe hypoglycemia are less frequent with SGLT2i and GLP1a than with insulin or sulfonylureas." (PMID 40717970, 2025). "Single-objective optimization: most RL models optimize only TIR but fail to balance other critical objectives such as reducing glycemic variability, preventing hypoglycemia, and minimizing insulin overuse." (PMID 40614090, 2025). "They proposed an insulin adjustment protocol, increasing the basal insulin dose (glargine U100) by 20% daily if the average blood glucose was greater than 140 mg/dL and decreasing by 20% in case of hypoglycemia (<70 mg/dL)." (PMID 39939862, 2025). "The possible explanation is that although immediate insulin administration is effective in lowering blood glucose, it may not rapidly improve the general health of these patients and may instead trigger complications such as hypoglycemia, which can increase the risk of death." (PMID 40060382, 2025). "Insulin lispro and Insulin aspart are the two major rapid-acting insulin analogs that emerged in the late 80s and 90s, each demonstrating an ability to reduce glycosylated hemoglobin levels and the frequency of hypoglycemia in patients." (PMID 40137145, 2025).
Hypoglycemia (continued). "IGF-2 demonstrates insulin-mimetic properties and induces hypoglycemia through its interaction with IGF receptors and insulin receptors." (PMID 41333493, 2025). "Laboratory investigations indicated hypogonadotropic hypogonadism, central hypothyroidism, and an insulin-induced hypoglycemia test suggested insufficient compensatory growth hormone secretion, while cortisol compensation was normal." (PMID 40529824, 2025). "Some participants who discontinued insulin experienced episodes of hypoglycemia, underscoring the need for careful monitoring." (PMID 41332894, 2025). "Congenital hyperinsulinism (HI) is a rare disease characterized by excessive insulin secretion that leads to severe hypoglycemia." (PMID 40917359, 2025). "Another study noted similar results when comparing euDKA to hyperglycemic DKA and attributed the prolonged time to anion gap closure to lower insulin infusion rates, presumably chosen to prevent hypoglycemia." (PMID 40900206, 2025). "Patients who received GLP‐1RA showed a significant reduction in body weight, a decrease in mean total insulin dose, and fewer episodes of hypoglycaemia." (PMID 40277315, 2025). "This study aimed to detect hypoglycaemia episodes and evaluate glucose dynamics and glycaemic variability in insulin-treated diabetic and healthy cats using a continuous glucose monitoring system (CGMS)." (PMID 41204810, 2025). "Our analysis showed no overall significant difference in the incidence of level 1 or level 2 hypoglycemia between once‐weekly and once‐daily insulin regimens." (PMID 40186384, 2025). "When glucose levels are expected to exceed 180 mg/dL, the system delivers automatic correction boluses, while suspending insulin delivery when hypoglycemia (<70 mg/dL) is predicted." (PMID 41010993, 2025). "The glycemic profile showed a fluctuating trend in blood glucose levels with frequent hypoglycemia episodes despite the low insulin requirement." (PMID 40244428, 2025). "Our case illustrates this paradox as insulin was needed to shift potassium but risked profound hypoglycemia." (PMID 41146800, 2025). "Since cortisol exerts critical metabolic effects by impairing insulin signaling, increasing gluconeogenesis, lipolysis, ketogenesis, and proteolysis, and decreasing glucose utilization, its deficiency might impair counter-regulatory defenses against hypoglycemia." (PMID 40729125, 2025). "On the other hand, it can exacerbate hypoglycemia with insulin, sulfonylureas and the glinides, which is of particular concern in older persons." (PMID 41331795, 2025). "Everolimus was found to downregulate insulin secretion by inhibition of the mTORC1/S6K pathway with subsequent improvement in hypoglycemia observed within 3–14 days of starting treatment." (PMID 40648766, 2025). "He would often fast until he became very hungry and then would end up eating a carbohydrate-dense meal, resulting in an over-aggressive insulin response with resultant severe hypoglycemia." (PMID 40395710, 2025). "A survey of individuals with type 1 diabetes traveling long distances found that 74% reported experiencing increased hypoglycemia and/or hyperglycemia during overseas travel, and 22% had run out of insulin at some point during their trip." (PMID 40901237, 2025). "Several studies have shown that the incidence of hypoglycemia during hyperglycemic crises depends on the dosage and amount of insulin received." (PMID 38594758, 2024). "Our results confirmed the glucose concentration-dependent effect of liraglutide on insulin secretion and hypoglycemia." (PMID 38509558, 2024). "A lower rate of severe hypoglycemia with IGlar than those treated with NPH insulin generates cost savings, resulting in significantly reduced additional costs of IGlar." (PMID 39877917, 2024). "By contrast, administration of serotonin receptor 2 antagonist (ketanserin) abolished the impact of serotonin to induce hypoglycemia, in concert with decreased insulin and GLP-1 secretion." (PMID 39264731, 2024).
Hypoglycemia (continued). "Late postprandial hypoglycemia (>4 h after a meal) following aerobic EXE is driven partly by circulating basal insulin concentrations." (PMID 38542818, 2024). "While dysregulated glucagon secretion by alpha cells plays a role in these conditions, it is also important to note that hypoglycemia in T1D occurs commonly after insulin administration." (PMID 39594662, 2024). "While the excessive secretion of insulin is essential for diagnosing insulinomas, delayed or inaccurate identification of hypoglycemia and other common presentations often result in severe consequences and mortality associated with insulinomas." (PMID 38952387, 2024). "Neonates have limited counterregulatory mechanisms against hypoglycemia, responding by reducing insulin secretion and increasing glucagon, epinephrine, growth hormone, and cortisol to mobilize glucose and fatty acids." (PMID 39006567, 2024). "Nocturnal asymptomatic hypoglycemia occurs in approximately 25% of diabetic patients treated with insulin therapy, according to one report, and elderly patients are particularly susceptible." (PMID 38933821, 2024). "The relative insulin excess increases glucose uptake and suppresses glucose production in the liver, despite the development of hypoglycemia." (PMID 38397994, 2024). "Upon analysis, the blood sugar was 41 mg/dL with undetectable insulin and C-peptide levels, consistent with hypoinsulinemic hypoglycemia." (PMID 38957156, 2024). "In 1996, genetic engineering enabled the development of novel long- and short-acting insulin analogs, which cleared the path for more physiological insulin therapy in terms of hypoglycemia and patient satisfaction." (PMID 39734941, 2024). "The DSME advocates for caregivers to ensure warmth and comfort following invasive procedures, such as replacing insulin pumps, establishing feeding and sleep routines, and maintaining vigilance for hypoglycemia, which are pivotal aspects of pediatric care." (PMID 39286453, 2024). "While concerns over hypoglycemia, difficulty in controlling blood glucose, and reluctance to start insulin infusion for intense glycemia control are the main barriers to achieving the glycemic target." (PMID 39700102, 2024). "Frequent and or/severe hypoglycemia was a common occurrence in both groups, and it was more common in subjects treated with insulin." (PMID 38331895, 2024). "Glucagon counteracts insulin-driven hypoglycemia by stimulating both glycogenolysis and gluconeogenesis in the liver, raising plasma glucose levels." (PMID 39594662, 2024). "The possibility of insulin-induced severe hypoglycemia after pramlintide therapy initiation is low in patients with T2DM or T1DM." (PMID 38338796, 2024). "Under insulin-induced hypoglycemia, we found that the concentration of numerous amino acids was reduced in Trpc5fx/0;DBH-Cre+ mice when compared with the control group (Trpc5fx/0;DBH-Cre–) or with plasma taken from saline injected Trpc5fx/0;DBH-Cre+ mice." (PMID 39375537, 2024). "Nonetheless, as it was our intention to create an experimental condition comparable to the clinical situation of insulin-induced hypoglycemia, at least in this study, we considered insulin injections to be inevitable." (PMID 38396718, 2024). "The laboratory analysis performed to investigate hypoglycemia revealed reduced levels of insulin and C-peptide." (PMID 39219869, 2024). "Ching-Hsiang Leung’s team reported that hypoglycemia is a risk factor for increased mortality in CRAB-infected patients and emphasized the importance of glycemic control, noting that insulin therapy is a major cause of hypoglycemia." (PMID 39403207, 2024). "Comparable results in the Trpc1/4/5/6–/– and wild-type mice also argue against an enhanced insulin-sensitive uptake of glucose into the mutant cells as an explanation for the aggravated hypoglycemia under insulin treatment." (PMID 39375537, 2024).
Hypoglycemia (continued). "KO mice exhibit disturbances in glucose metabolism with fasting hypoglycemia and decreased insulin levels in both sexes at 9 weeks." (PMID 38519536, 2024). "Multiple risk factors contribute to increased risk of SH in older adults including long disease duration, decline in hypoglycemia awareness, renal impairment, cognitive dysfunction, and insulin use." (PMID 38607977, 2024). "If glycemia falls to <14 mmol/L despite glucose infusion, one should reduce the intravenous insulin infusion rate to 0.05 units/kg/h to avoid hypoglycemia." (PMID 38786741, 2024). "We conducted a comprehensive analysis to assess the risk of hypoglycemia associated with GLP-1/GIP receptor agonists and weekly insulin analogs, using daily insulin as the baseline comparator." (PMID 39335457, 2024). "Detectable insulin concentrations concurrent with hypoketotic hypoglycemia as well as a robust glucose response (>30 mg/dL increase) to glucagon (1 mg) administration are diagnostic of hyperinsulinism." (PMID 38792494, 2024). "The test insulin and the comparator are both then titratedto reach this glycemic target so other outcome measures such as hypoglycemia or weight gaincan be properly evaluated." (PMID 38224978, 2024). "All insulin was ceased, and the exercise-induced and postprandial hypoglycemia were initially managed with reinforcement of dietary advice for controlled portions of low glycemic index, complex carbohydrates and avoidance of excessive simple carbohydrates." (PMID 39450137, 2024). "Responses of vasopressin to insulin-induced hypoglycemia were found to be significantly lower in obese men than in normal weight men." (PMID 39769071, 2024). "Previous studies, including our own, had shown that Fos expression, a marker of cellular activity within the rat adrenal medullary cells increased significantly in response to 2DG-induced glucoprivation and insulin-induced hypoglycaemia." (PMID 38392992, 2024). "Due to its ability to rapidly reverse hypoglycemia, significant effort has been expended to develop stable glucagon formulations to treat hypoglycemia as well as a partner to insulin in bihormonal pump therapy." (PMID 38477666, 2024). "In people who were on insulin and/or sulphonylurea with HbA1c <7.0% (53 mmol/mol) and/or inpatient hypoglycaemia, the deintensification rate was slightly higher at 34.3%." (PMID 38387535, 2024). "So, one of the primary goals of the present study was to investigate the impact of recurrent severe insulin-induced hypoglycemia on the cognitive deficits and the transient and permanent brain injuries in rat." (PMID 39004753, 2024). "It provided advice on carbohydrates and insulin during exercise, information on hypoglycemia treatment, pre- and postexercise advice, and an educational food guide regarding exercise management." (PMID 39078700, 2024). "Insulin remains the most potent glucose-lowering agent but carries increased risks of hypoglycemia and weight gain." (PMID 39723311, 2024). "During the hypoglycemia period induced with insulin, the vital signs of the patients were stable, and hypoglycemic symptoms were mild and completely reversed upon return to euglycemia." (PMID 39629677, 2024). "Although he only started with rapid-acting insulin analogue before meals, he presented spontaneous episodes of hypoglycemia just before the morning hydrocortisone dose, due to an underdosed glucocorticoid intake." (PMID 39091607, 2024). "Hypoglycemia (HG) is a major threat in T1D patients and commonly occurs in clinical practice in approximately 90% of all patients who receive insulin." (PMID 38475089, 2024). "The two groups’ rates of combined clinically significant events or severe hypoglycemia were similar, concluding that once-weekly insulin icodec achieves better glycemic control than once-daily insulin glargine U100." (PMID 38672255, 2024).